CD300LD-AS1 (CD300LD antisense RNA 1)
Synonyms: C17orf77; FLJ31882
Gene: Long non-coding RNA gene on chromosome 17 (74,584,679 to 74,626,003, forward strand). Ensembl gene ENSG00000182352.
Subcellular location: Secreted
Diseases named in the same sentence as CD300LD-AS1 in open-access papers:
CD300LD-AS1 is named in the same sentence as 1 disease in open-access papers, as found by Europe PMC text mining. Sharing a sentence is not in itself a finding about the gene and the disease.
CD300LD-AS1 shares sentences with these, for which no sentence is quoted: cancer (2 papers).